SAPCD1 (suppressor APC domain containing 1)
Synonyms: C6orf26; NG23
Tractability: No criterion of Open Targets' tractability assessment is met for any kind of drug.
Gene: Protein-coding gene on chromosome 6 (31,762,656 to 31,764,851, forward strand). Ensembl gene ENSG00000228727.
Subcellular location (Human Protein Atlas): Vesicles; Cell Junctions
Gene Ontology:
Molecular function: protein binding
Genetic constraint (gnomAD): Loss-of-function variants: 14 observed, 18.76 expected, observed/expected ratio (o/e) 0.75, 90% interval 0.49 to 1.17. The upper end of that interval is the gene's LOEUF score, 1.17, which puts it in group 5 of 6, group 1 being the genes least tolerant of losing a copy. Missense variants: 165 observed, 198.08 expected, observed/expected ratio (o/e) 0.83, 90% interval 0.73 to 0.95. Synonymous variants: 72 observed, 81.19 expected, observed/expected ratio (o/e) 0.89, 90% interval 0.73 to 1.08.
Homologues: Orthologues: chimpanzee SAPCD1 (100% identical), macaque SAPCD1 (94% identical), pig SAPCD1 (78% identical), dog SAPCD1 (74% identical), rabbit SAPCD1 (70% identical), mouse Sapcd1 (58% identical), guinea pig SAPCD1 (56% identical), rat Sapcd1 (49% identical), Drosophila melanogaster CG3880 (20% identical), Caenorhabditis elegans T01B6.1 (19% identical). Paralogues in human: SAPCD2 (28% identical).
Diseases named in the same sentence as SAPCD1 in open-access papers:
SAPCD1 is named in the same sentence as 5 diseases in open-access papers, as found by Europe PMC text mining. Sharing a sentence is not in itself a finding about the gene and the disease. The quoted sentences say what the papers report.
breast carcinoma (1 paper, 2022). "The suppressor APC domain containing 1 (SAPCD1) gene is involved in DNA repair and is underexpressed in breast cancer tissue." (PMID 35295987, 2022).
Kaposi's sarcoma (1 paper, 2025). A malignant neoplasm characterized by a vascular proliferation which usually contains blunt endothelial cells. "Polymorphisms in HLA-DMB antigen and SAPCD1, another class III MHC gene, at chromosome 6p21.3 had links to Kaposi sarcoma." (PMID 39885374, 2025).
lung carcinoma (1 paper, 2020).
SAPCD1 also shares sentences with these, for which no sentence is quoted: macular degeneration (1 paper); rheumatoid arthritis (1).